OTUD7B (OTU deubiquitinase 7B)
Diseases named in the same sentence as OTUD7B in open-access papers (continued):
Sharing a sentence is not in itself a finding about the gene and the disease.
hypertrophic cardiomyopathy (1 paper, 2025). A condition in which the myocardium is hypertrophied without an obvious cause. "Bulk RNA-seq data from both Ang II-induced hypertrophic mice and hypertrophic cardiomyopathy patients further confirmed OTUD7B as one of the significantly downregulated members of the OTU family." (PMID 40158182, 2025). "First, the downregulation of OTUD7B in hypertrophic cardiomyopathy samples was identified from publicly available single-cell sequencing data rather than clinically acquired data." (PMID 40158182, 2025). "At the single-cell level, we observed downregulation of OTUD7B in hypertrophic cardiomyopathy patient samples." (PMID 40158182, 2025).
leukemia (1 paper, 2023). A malignant (clonal) hematologic disorder, involving hematopoietic stem cells and characterized by the presence of primitive or atypical myeloid or lymphoid cells in the bone marrow and the blood. "In addition, we report an oncogenic function for OTUD7B in leukemia by similarly controlling K63-linked GβL ubiquitination and mTORC2 activity in governing leukemia cell proliferation." (PMID 36672466, 2023). "Consistent with an oncogenic role of OTUD7B in facilitating leukemia cell proliferation, inhibiting OTUD7B by 7Bi reduced the proliferation of HL60, K562 and THP1 cells." (PMID 36672466, 2023). "Together, these data not only support the critical role of OTUD7B in governing leukemia cell proliferation but also confirm 7Bi as a potential OTUD7B small molecule inhibitor in suppressing leukemia cell proliferation." (PMID 36672466, 2023). "We further found OTUD7B also governed various leukemia cell proliferation and 7Bi treatment efficiently reduced leukemia cell proliferation in vitro." (PMID 36672466, 2023). "This promoted us to examine the roles of OTUD7B in leukemia cells." (PMID 36672466, 2023). "7Bi treatment increased K63-linked GβL ubiquitination at endogenous levels in K562 cells, further supporting OTUD7B may govern leukemia cell proliferation through a similar OTUD7B/GβL/Akt signaling axis as in NSCLC." (PMID 36672466, 2023). "Furthermore, we report in leukemia cells, either genetic depletion or 7Bi-mediated pharmacological inhibition of OTUD7B reduces Akt-pS473 via inhibiting the OTUD7B/GβL signaling axis." (PMID 36672466, 2023).
prostate carcinoma (1 paper, 2024). A carcinoma that arises from epithelial cells of the prostate gland. "Taken together, OTUD7B promotes the proliferation, and autophagy, and inhibits apoptosis of prostate cancer cells via the AKT/mTOR signaling pathway." (PMID 38935308, 2024). "Therefore, we downregulated OTUD7B using siRNA and confirmed the role of OTUD7B in PC3 prostate cancer cells." (PMID 38935308, 2024).
turban tumour syndrome (1 paper, 2015). "It has been determined that many DUBs, such as cylindromatosis (turban tumour syndrome) (CYLD), A20, and OTU deubiquitinase 7B (OTUD7B), negatively regulate NF-ĸB signalling by ubiquitin deconjugation of key signalling molecules such as RIP1." (PMID 25595906, 2015).
viral infection (1 paper, 2014). "So far, several deubiquitinases such as DUBA, OTUB1/2, UCHL1, and OTUD7B have been reported to cleave TRAF3 ubiquitin chains in response to viral infection." (PMID 24763515, 2014). "We first screened the reported deubiquitinases for TRAF3 and found that HSCARG interacted with OTUB1 more potently than OTUB2, UCHL1, OTUD7B, and USP25, and this interaction was enhanced by viral infection." (PMID 24763515, 2014).
cancer (23 papers, 2015 to 2025). A tumor composed of atypical neoplastic, often pleomorphic cells that invade other tissues. "OTUD7B upregulation predicts an increased risk for cancer metastasis in LUSC and LAD patients." (PMID 31572671, 2019). "Collectively, these findings indicate that OTUD7B is upregulated in cancer and contributes to accelerated tumor growth, aligning with poor prognostic outcomes, substantiating the results of this study." (PMID 40746896, 2025). "Studies focusing on cancer have generally concluded that OTUD7B is typically expressed at high levels in tumor cells, often as a result of genomic amplification 18, 20, where it variously functions to promote tumorigenesis." (PMID 39990225, 2025). "Consistent with the literature showing downregulation in HCC, we observed that staining for OTUD7B was frequently reduced in cancer compared to normal liver tissues." (PMID 39990225, 2025). "OTUD7B has been reported to regulate antiviral immunity, inflammation, and cancer cell proliferation." (PMID 40158182, 2025). "OTUD7B is frequently amplified in various malignant tumors, including those affecting the stomach, liver, breast, pancreas, and prostate, where it promotes tumor initiation and progression." (PMID 40746896, 2025). "In these cancers, the upregulation of OTUD7B promotes the stabilization and activation of TRAF3, estrogen receptor α, and N1ICD, leading to uncontrolled cell growth and tumor formation." (PMID 37371581, 2023). "This compound, 7Bi, efficiently inhibited OTUD7B activity both in cells and in vitro, leading to reduced cancer cell proliferation." (PMID 36672466, 2023). "Together, our study identifies the first putative OTUD7B inhibitor showing activities both in cells and in vitro, with promising applications as a therapeutic agent in treating cancer with OTUD7B overexpression." (PMID 36672466, 2023). "Further investigation is warranted to explore the potential of OTUD7B as a therapeutic target in human cancers by disrupting its interaction with LEF1 and inhibiting Wnt signaling pathway activation." (PMID 37371581, 2023). "Consistently, upregulation of OTUD7B positively correlates with cancer progression and poor prognosis in lung squamous carcinoma and adenocarcinoma." (PMID 33670113, 2021). "Our data unraveled a pivotal role of OTUD7B in gene transcription, cell proliferation, and cancer metastasis by modulating LSD1 stability and its assembly into corepressor complex." (PMID 34050636, 2021). "Its increased expression has been reported in lung squamous carcinoma and adenocarcinoma compared to normal tissue; in the same cancer model, OTUD7B promoted cell proliferation, migration and metastasization." (PMID 33371395, 2020). "Although some evidence revealed the role of OTUD7B in cancer progression, the molecular mechanisms of OTUD7B participation in invasion and metastasis in NSCLCs remains elusive." (PMID 31572671, 2019). "Since many anti-cancer drugs achieve effects through inducing apoptosis, there may be further value in investigating their potential synergy with approaches to manipulate OTUD7B expression in HCC." (PMID 39990225, 2025). "Second, a review of the existing literature indicated that while OTUD7B has been studied in several types of cancers, its role in esophageal cancer remains unclear." (PMID 40746896, 2025). "OTUD7B plays a diverse role in cancer and vascular diseases." (PMID 38474013, 2024). "OTUD7B is a member of the deubiquitinase family that undergoes a post-translational transformation process, which is essential for cell stability and signaling and is known to play a critical role in cancer." (PMID 38935308, 2024). "Studies have exhibited that OTUD7B stimulates cancer progression in multiple human cancers." (PMID 37371581, 2023). "However, caution needs to be applied when developing and using OTUD7B inhibitors, especially for cancers where the Wnt signaling pathway is dysregulated." (PMID 37371581, 2023).
cancer (continued). "Genomic amplification of OTUD7B is frequently found across human cancers." (PMID 34050636, 2021). "Recent studies suggested that OTUD7B may promote cancer progression by activating oncogenic pathways including EGFR and mTORC2/Akt signaling." (PMID 33670113, 2021). "Which is the dominant pathway for OTUD7B in cancer cell migration and invasion?" (PMID 33198776, 2020). "Strategies to silencing OTUD7B in carcinoma tissues may inform the development of novel therapies to fight against LUSC and LAD." (PMID 31572671, 2019). "In addition, an oncogenic function of OTUD7B in cancer has been well demonstrated." (PMID 36672466, 2023). "This discovery implies that OTUD7B potentially participates in modulating the HIF-1α signaling pathway, a key regulator in the survival, proliferation, and metastatic spread of cancer cells under hypoxic conditions." (PMID 40746896, 2025). "Second, while the study focused on the interplay between OTUD7B, METTL14, and HIF-1α, it is important to recognize that cancer progression is a multifaceted process involving intricate interactions among multiple genes and factors." (PMID 40746896, 2025). "Together, our study provides the chemical structure for a possible OTUD7B inhibitor that can be further improved by medicinal chemistry or PROTAC/DUBTAC approaches, with potential as viable therapeutic agents in treating cancer with OTUD7B overexpression." (PMID 36672466, 2023). "Of 16 additional cancer cell lines tested, all lines exhibited significant LSD1 decrease when OTUD7B was depleted." (PMID 34050636, 2021). "For example, there are some DUBs that are only identified in the cancer cells like USP3, USP4, and OTUD7B." (PMID 33718328, 2021). "Previous research has also reported that OTUD7B regulates hypoxia inducible factors 1α and 2α protein, which are known effective regulators of VEGF and angiogenesis in cancer." (PMID 31572671, 2019). "Besides OTUB1, other DUBs, such as USPs family (USP1, USP7, USP8, USP15, USP22), OTUs family (OTUD7B, OTUD6B, A20, and OTUB2) and other DUBs have been identified to regulate the progression of various cancers and applied for clinical cancer therapy." (PMID 35715413, 2022). "Similarly, there is downregulation of OTUD7B and TAX1BP1 in various cancers, which greatly contributes to hyperactivation of NF-κB signalling." (PMID 25595906, 2015). "The Cancer Genome Atlas (TCGA), Cancer Cell Line Encyclopedia (CCLE), and Sequence-based RNA Adenosine Methylation Site Predictor (SRAMP) databases were used to evaluate the expression of OTUD7B in ESCC and its correlation with methyltransferase-like 14 (METTL14) and HIF-1α." (PMID 40746896, 2025). "Considering its oncogenic function in cancer and its great potential as a cancer drug target but without available inhibitors, here we aim to rely on artificial intelligence AtomNet to screen for small molecule OTUD7B inhibitors." (PMID 36672466, 2023).
tumor (21 papers, 2013 to 2025). "We also investigated association between OTUD7B expression and chemotherapeutic drugs anti-tumor activity in vitro." (PMID 35154465, 2022). "The mechanism of the association between OTUD7B and the occurrence and development of tumor cells is unclear, and the specific function of its action on cells has not been fully clarified." (PMID 31747939, 2019). "Although accumulating studies have revealed that OTUD7B plays a pivotal role in tumor progression, the underlying molecular mechanism of OTUD7B in the development of PC remains unclear." (PMID 36351890, 2022). "In HCC, for example, decreased OTUD7B expression was related to increased tumor volume, presence of satellite nodules, vascular invasion, and early recurrence." (PMID 40469292, 2025). "OTUD7B/Cezanne, a member of the ovarian tumor (OTU) domain-containing family of deubiquitinases (DUBs), is a critical regulator of various cellular processes, including DNA damage response and immune regulation." (PMID 37371581, 2023). "Knockdown of OTUD7B significantly inhibited tumor growth in vivo, while the restoration of ERα expression abolished the inhibition induced by OTUD7B depletion." (PMID 34035221, 2021). "We performed H&E staining to verify tumor tissues and immunohistochemistry to detect the expression of OTUD7B, TRAF3, NIK, Ki67, MMP9 and IL-2 in the xenografted tissues." (PMID 33198776, 2020). "The NCI-H358 tumor bearing mouse model was established to further examine the tumorigenic role of OTUD7B." (PMID 31572671, 2019). "NCI-H358 tumor model demonstrated OTUD7B is required for lung tumor progression by facilitating activation of Akt signaling." (PMID 31572671, 2019). "OTUD7B is a member of the OTU family of deubiquitinases, which is associated with the tumor rapid progress and deterioration." (PMID 31747939, 2019). "We found that mRNA expression levels of OTUD7B and miR-1180 were inversely related in tested tumor tissues." (PMID 29416635, 2018). "The data showed that tumor volumes of the tested TNBC cells post-implantation for 4 weeks are negatively correlated with OTUD7B mRNA levels." (PMID 29416635, 2018). "In addition, depletion of OTUD7B by using in vivo-optimized RNAi also significantly reduced tumor growth." (PMID 34035221, 2021). "OTUD7B overexpression dramatically promoted tumorigenicity and tumor growth speed in nude mice." (PMID 31572671, 2019). "Studies show that NS5A binds to the ovarian tumor protein, deubiquitinase 7B (OTUD7B) and enhances OTUD7B DUB activity, which may contribute to viral replication and infection." (PMID 31396277, 2019). "Furthermore, western blotting analysis revealed that the expression of CYLD, TAX1BP1 and OTUD7B dramatically decreased in the miR-500–overexpressing tumours but increased in miR-500–silenced tumours." (PMID 25595906, 2015). "ANKRD40, HNRNPF, IQGAP2, OTUD7B, and THAP5 mutations were detected in 1 tumor, each." (PMID 24223926, 2013). "Therefore, OTUD7B upregulation may suppress tumor growth via negatively regulating NF-κB-related pathway in TNBCs." (PMID 29416635, 2018). "To further prove the mechanisms of OTUD7B inhibiting LCL161-induced invasion and metastasis in vivo, we performed IHC assay in the tumor nodules by using a subcutaneous tumor mode." (PMID 33198776, 2020). "Knockdown of OTUD7B in NCI-H358 cells significantly decreased Akt phosphorylation at S473 and inhibited tumor growth." (PMID 31572671, 2019). "OTUD7B (also called Cezanne-1) is a typical member of the subfamily of OTU DUBs29,30 and has been documented to regulate T-cell activation and tumor development by NF-κB, mTOR, or hypoxia signaling." (PMID 30405104, 2018).
tumor (continued). "The results showed that OTUD7B, TNIP2 and BAD, which are closely correlated with cell survival and apoptosis progression in tumours, were three putative targets of miR-1180." (PMID 26928365, 2016). "This study represents one of several reports showing both negative and positive effects of OTUD7B on tumor cell invasiveness 18, 23, 42, 63, a tumorigenic phenotype which we have not addressed here." (PMID 39990225, 2025). "However, both OTUD7B and TNFAIP3 can exert anti-tumor effects by inhibiting the NF-κB signaling pathway in HCC." (PMID 40469292, 2025). "However, the role of OTUD7B in tumor growth and metastasis signals is still not clear." (PMID 31572671, 2019). "Additionally, the results of expression analysis on the data of Chinese Human Proteome Project (CNHPP) (110 paired tumor and nontumor tissues of clinical early‐stage HCC) showed consistently upregulation of protein level of OTUs (including OTUD7B, OTUD6B, ALG13, OTUB1, OTULIN) in HCC tissues." (PMID 32328410, 2020).
infection (5 papers, 2019 to 2025). The state of being infected such as from the introduction of a foreign agent such as serum, vaccine, antigenic substance or organism. "OTUD7B (Cezanne) prevents tumor necrosis factor (TNF)-induced apoptosis of dendric cells in infection and facilitates T cell activation and inflammatory responses by regulating Zap70 ubiquitination." (PMID 39985644, 2025). "Here, we uncover that the ovarian tumor deubiquitinating enzyme 7b (OTUD7b) prevents TNF-induced apoptosis of DCs in infection, resulting in efficient priming of pathogen-specific CD8+ T cells." (PMID 37516734, 2023). "Among these, one group containing OTUB1, OTUB2, OTUD4, OTUD5, OTUD6B, and OTUD7B showed obvious upregulation 6 h post-infection, followed by downregulation 12 h post-infection." (PMID 37650650, 2023). "Transcriptomic profiling revealed infection-induced upregulation of DUBs, particularly USP25, USP46, and OTUD7B." (PMID 40899844, 2025). "First data in a proteome analysis from S. aureus infected macrophage-like cell line THP1 showed a decrease in the abundance of the analyzed proteins USP7, USP48, UCHL3, OTUD7B, and SENP1 (data not shown) which might indicate an intracellular role of Spls during infection." (PMID 39985644, 2025).
adenocarcinoma (2 papers, 2019 to 2020). A common cancer characterized by the presence of malignant glandular cells. "OTUD7B is highly expressed in both lung squamous carcinoma and adenocarcinoma and correlates with a worse prognosis." (PMID 31572671, 2019).
OTUD7B also shares sentences with these, for which no sentence is quoted: squamous carcinoma (2 papers); breast invasive carcinoma (1); chronic myelogenous leukemia (1); Hyperglycemia (1); lymph node metastasis (1); myocardial infarction (1); non-small cell lung carcinoma (1); retinal degeneration (1); Stroke (1); Thyroid adenoma (1); triple-negative breast carcinoma (1).